PDGFC (platelet derived growth factor C)
Diseases named in the same sentence as PDGFC in open-access papers (continued):
Sharing a sentence is not in itself a finding about the gene and the disease.
tumor (continued). "Platelet-derived growth factor-C (PDGF-C) mediates the angiogenic properties of TAFs and has been found to be upregulated in tumor cells resistant to anti-VEGF antibodies." (PMID 38239394, 2023). "miR-375 inhibits the platelet-derived growth factor C (PDGFC) and then inhibits the tumor angiogenesis." (PMID 37369681, 2023). "In a transgenic mouse model overexpressing platelet derived growth factor C (PDGF C), LNA-antimiR-124 suppressed miR-124 signaling and expression of cognate target genes, leading to reduced hepatic fibrosis and even inhibited tumor formation." (PMID 31652839, 2019). "PDGFB and PDGFRB are less expressed relatively to PDGFC in perinecrotic zone, and also in comparison to PDGFRA in cellular tumour block." (PMID 29127351, 2017). "Further confirmation on different metabolic pathways in ICM and ESC comes from the observation that PDGFC and HIF1a, which contribute to the expression of LDHA and promote anaerobic glycolysis in tumor cells, were downregulated in bovine ICM cells." (PMID 26681441, 2015). "It was found that expression of IGF1, HGF, PDGFC, and PDGFD were significantly increased 5.32-, 10.21-, 6.24-, and 3.24-fold in tumor tissues, respectively, when compared with arachnoidal tissue by qRT-PCR." (PMID 23285163, 2012). "By dividing the tumours into classical PTC and more aggressive PTCs we found that PDGFC was the only PDGF family member (including ligands and receptors) that was significantly differentially expressed between the two tumour groups (p = 0.006)." (PMID 19968886, 2009). "It has been demonstrated that PDGFC in PTC specimens is expressed mainly in the cell membrane, the cytosol and in the perinuclear area of the tumour cells, and that the ~43 kDa non-SUMO1 modified form is the predominant." (PMID 19968886, 2009). "PDGFC may directly trigger PDGFRA signaling in CAF-C7, in keeping with our data showing increased deposition of ECM and activation of PI3K signaling at tumor margin." (PMID 39870619, 2025). "The ligand-receptor pairs IGF2-IGF1R, PDGFD-PDGFRB and PDGFC-PDGFRA were enriched between these two cell types, implicating Scissor+ tumor cells may play an important role in promoting expansion of CAFs." (PMID 40098972, 2025). "Similarly, ITGAV, PDGFC, PDGFD, and COL1A1—the most abundant collagen in human tissues—are often highly expressed in tumor cells, and inhibiting their expression can effectively suppress cell proliferation, migration, and invasion." (PMID 41227351, 2025). "Interestingly, we found that ESM1 and PDGFB are expressed in the same tumor regions, while PDGFA and PDGFC seem to be mutually exclusive with PDGFB and ESM1." (PMID 39773984, 2025). "Generation of two independent ZR-75-1-shPDGFC lines confirmed that downregulation of PDGFC does not impact tumor cell proliferation in vitro but, following intravenous inoculation, significantly reduces the number of single DTCs and larger lesions." (PMID 36914817, 2023). "We also observed that tumor and endothelial cells released vascular endothelial growth factors, including VEGFC and VEGFA, as well as platelet-derived growth factors, including PDGFA and PDGFC." (PMID 37333982, 2023). "CAF is an abundant source of VEGFA and other pro-angiogenetic factors such as platelet-derived growth factor C (PDGFC), fibroblast growth factor 2 (FGF-2), and C-X-C motif chemokine 12 (CXCL12/SDF-1), which directly or indirectly regulates tumor neovascularization." (PMID 35327514, 2022). "CAF-derived PDGFC, together with VEGFA, mediates tumor growth, metastasis, and angiogenesis." (PMID 35327514, 2022). "In fact, CAFs directly enhance tumor angiogenesis through producing pro-angiogenic factors like vascular endothelial growth factor A (VEGFA), fibroblast growth factor 2 (FGF2), CXCL12, and PDGFC." (PMID 36465388, 2022).
tumor (continued). "Concerning HCC, it has been confirmed that the platelet-derived growth factors (PDGF, including PDGFA, PDGFB, PDGFC, and PDGFD) participate in modulating the tumor development and chemoresistance by interacting with its receptor PDGFR and activating the downstream signaling pathway." (PMID 36463115, 2022). "Similarly, we identified that SLUG expression in GIST cells was regulated by paracrine PDGFC secretion by CAFs, which led to PDGFRA signaling in the tumor cells." (PMID 33603171, 2021). "To verify whether the angiogenic genes were involved in Roquin2-mediated tumor angiogenesis, we silenced EDN1 and PDGFC using shRNA lentiviruses in MDA-MB-231/shRoquin2 cells." (PMID 34345214, 2021). "In turn, we found that PDGFC secreted by CAFs contributed to GIST growth, migration, and invasion via PDGFRA activation, suggesting that CAF-produced PDGFC can activate PDGFRA signaling in GIST, and this crosstalk between CAFs and GIST cells leads to a more aggressive tumor phenotype." (PMID 33603171, 2021). "Moreover, CM from these CAF cultures increased T1 proliferation, while these effects were abrogated by PDGFC neutralizing antibody, suggesting that PDGFC secretion from CAF lines isolated from KIT and PDGFRA mutant GISTs modulates tumor cell growth." (PMID 33603171, 2021). "When Roquin2 and EDN1/PDGFC were co-knockdown, HUVEC migration was restored to comparable to the scramble control group, suggesting that the angiogenic genes are indeed involved in Roquin2-mediated tumor angiogenesis." (PMID 34345214, 2021). "Alternatively, these DCs could modulate the tumor microenvironment by secreting vasculogenic factors such as vascular endothelial growth factor D (VEGF-D), platelet-derived growth factor C (PDGFC), and angiopoietin 1 (ANGPT1)." (PMID 31731454, 2019). "The PDGFC/PDGFR complex can trigger downstream signal transduction pathways including extracellular signal-regulated kinase 1/2 (ERK) and phosphatidylinositol 3-kinase (PI3K)/AKT, inducing tumor progression, angiogenesis, and survival in a variety of tumor cells." (PMID 36979654, 2023). "Differently, PDGFC is less expressed in microvascular proliferation in comparison to all other GBM regions aside from hyperplastic blood vessel and leading edge, and similarly to PDGFA and PDGFRA, it bears a preferential expression in cellular tumour bulk over leading edge." (PMID 29127351, 2017). "Only PDGFC expression could differentiate classical PTCs from clinically aggressive and poorly differentiated PTCs, but gene expression profiling suggest that this most probably is related to the presence of tumour-infiltrating lymphocytes rather than to the current classification of the tumours." (PMID 19968886, 2009). "Intriguingly, the prognostic value of PDGFs was dependent on the tumor vs. the stromal expression of the analyzed proteins, i.e., stromal PDGFD could predict CSS; in contrast, the tumor but not the stromal PDGFC could predict CSS." (PMID 33918816, 2021).
cancer (40 papers, 2004 to 2025). A tumor composed of atypical neoplastic, often pleomorphic cells that invade other tissues. "Rp Dematteo’s team found that Cancer-associated fibroblast secretion of PDGFC promotes gastrointestinal stromal tumor growth and growth metastasis." (PMID 39234397, 2024). "PDGFC-encoded platelet-derived growth factor C was reported to promote angiogenesis, cancer cell proliferation, invasion, and metastasis." (PMID 36092919, 2022). "PDGFRα, the primary receptor for PDGFC, was inhibited using a PDGFRα inhibitor, which effectively suppressed the ability of cancer cell-CM to promote NRG1 expression in fibroblasts." (PMID 41213930, 2025). "Studies have reported that PDGFC derived from cancer cells is vital for the activation of fibroblasts, which promotes the lung colonization of BC cells." (PMID 41213930, 2025). "ELISA further confirmed that the CM from cancer cells contained higher levels of PDGFC compared to that from normal epithelial cells." (PMID 41213930, 2025). "Platelet-derived growth factor-C (PDGF-C), a key growth factor in cancer progression, plays a crucial role in promoting growth, angiogenesis, and tumorigenesis in various types of cancers." (PMID 39457720, 2024). "Platelet-derived growth factor-C (PDGF-C) belongs to a superfamily of growth factors that are involved in the stimulation of the growth, angiogenesis, and tumorigenesis of various cancers." (PMID 35406382, 2022). "Among Roquin2 targets, we chose four angiogenic genes (ENG, EDN1, VEGFB, and PDGFC) based on two criteria: 1) they are commonly downregulated in different types of cancer cells; and 2) they are among the most affected genes by Roquin2." (PMID 34345214, 2021). "Associations of NRP2, NRP1 and several NRP ligands (i.e., PDGFC and PDGFD) that have been implicated in cancer progression were analyzed." (PMID 33918816, 2021). "Moreover, CAF-derived PDGFC can facilitate the EMT of cancer cells and increase matrix metalloproteinase 2 (MMP2) expression through the PDGFRA-mitogen-activated protein kinase/extracellular signal-regulated kinase (MAPK/ERK) pathway." (PMID 40501228, 2025). "Knockdown of FTO suppressed cancer growth in a mouse xenograft model by increasing the m6A level of platelet‐derived growth factor C (PDGFC) mRNA, promoting PDGFC mRNA degradation by binding to YTHDF2, decreasing PDGFC secretion, and inhibiting the AKT signaling pathway." (PMID 40448344, 2025). "Previous studies showed that high expression levels of PDGFC, SOX9, BCL11A, and DIO2 were associated with poor response to chemotherapy in cancer cells and short survival time of various patients, which could be regarded as negative prognostic factors." (PMID 36092919, 2022). "Other genes that showed potential association with cancer pain in HNSCC patients included PIK3C2G (rs10770367, p value = 1.10 × 10−3), TCRA (rs6572493, p value = 2.84 × 10−3), PDGFC (rs6845322, p value = 4.88 × 10−3), and CD247 (rs2995082, p value = 7.79 × 10-3)." (PMID 26872611, 2016). "Furthermore, CAF-derived PDGFC promotes epithelial-mesenchymal transition (EMT) in cancer cells as well as matrix metalloproteinase 2 (MMP2) expression through the PDGF receptor A (PDGFRA)-mitogen-activated protein kinase/extracellular signal-regulated kinase (MAPK/ERK) pathway." (PMID 40501228, 2025). "Furthermore, the activation of AKT/mTOR signaling by NRG1 induces high expression of PDGFC in cancer cells, which in turn promotes the activation of fibroblasts and NRG1 expression through the release of PDGFC, forming a positive feedback loop between NRG1 and PDGFC." (PMID 41213930, 2025). "PDGFC may be related to the occurrence and development of various malignant tumors." (PMID 39225567, 2024).
cancer (continued). "The down-regulated gene PDGFC is a receptor with tyrosine-kinase activity that has roles in the regulation of many biological processes including embryonic development, angiogenesis, cell proliferation and differentiation, and contribute to the pathophysiology of some diseases, including cancer." (PMID 22912686, 2012). "In turn, cancer cell-derived PDGFC promotes fibroblast activation and high NRG1 expression, forming a positive feedback loop between NRG1 and PDGFC." (PMID 41213930, 2025). "Some of the crucial genes in this overlap include VEGFA, PDGFC and FN1 that were known to be involved in angiogenesis in different types of cancers." (PMID 32720467, 2020). "The invasive effects of MMP13 on cancer cells can be mediated through six novel targets, including the inactivation of chemokine C-C motif ligand 2 (CCL2) and CCL7, activation of platelet-derived growth factor-C (PDGF-C) and cleavage of SAA3, osteoprotegerin (OPG), CutA and antithrombin III." (PMID 35884405, 2022). "Again genes involved in other cancer-relevant processes such as cell proliferation, migration, differentiation, apoptosis, or cytoskeletal remodeling were among the driver candidates (all underexpressed with reduced copy number: ARHGAP18, DUSP10, PAK7, PDGFC, RNF217)." (PMID 31682594, 2019).
kidney disease (3 papers, 2016 to 2024). "Consuming koumiss has been shown to effectively repair glomerular damage and prevent chronic liver and kidney diseases by increasing platelet-derived growth factor c (PDGF-c) and platelet-derived growth factor receptor alpha (PDGFR-α) expression." (PMID 37927510, 2023).
cardiovascular disease (2 papers, 2019 to 2020). "PDGFC rs1425486 has not been previously associated with cardiovascular disease related outcomes." (PMID 33171725, 2020).
PDGFC also shares sentences with these, for which no sentence is quoted: steatosis (5 papers); ischemic stroke (3); osteosarcoma (3); chondrosarcoma (2); endothelial dysfunction (2); Ewing sarcoma (2); liver cirrhosis (2); lung cancer (2); Stroke (2); adenoma (1); alopecia (1); atrial fibrillation (1); cholestasis (1); Cirrhosis (1); classical Hodgkin lymphoma (1); colorectal (1); coronary disease (1); diabetic nephropathy (1); dilated cardiomyopathy (1); emphysema (1); esophageal cancer (1); gastric cancer (1); gastrointestinal stromal tumor (1); glomerulonephritis (1); glomerulopathy (1); glomerulosclerosis (1); Glucose intolerance (1); hemangiosarcomas (1); hemorrhage (1); Hyperglycemia (1).
A further 25 diseases each share a sentence with PDGFC in 1 paper.